RBM7 (RNA binding motif protein 7)
Description:
RNA-binding subunit of the trimeric nuclear exosome targeting (NEXT) complex, a complex that functions as an RNA exosome cofactor that directs a subset of non-coding short-lived RNAs for exosomal degradation. NEXT is involved in surveillance and turnover of aberrant transcripts and non-coding RNAs. Binds preferentially polyuridine sequences and associates with newly synthesized RNAs, including pre-mRNAs and short-lived exosome substrates such as promoter upstream transcripts (PROMPTs), enhancer RNAs (eRNAs), and 3'-extended products from small nuclear RNAs (snRNAs). Participates in several biological processes including DNA damage response (DDR) and stress response. During stress response, activation of the p38MAPK-MK2 pathway decreases RBM7-RNA-binding and subsequently the RNA exosome degradation activities, thereby modulating the turnover of non-coding transcriptome. Participates in DNA damage response (DDR), through its interaction with MEPCE and LARP7, the core subunits of 7SK snRNP complex, that release the positive transcription elongation factor b (P-TEFb) complex from the 7SK snRNP. In turn, activation of P-TEFb complex induces the transcription of P-TEFb-dependent DDR genes to promote cell viability.
Tractability: PROTAC: ubiquitination databases record sites on it; its protein half-life has been measured.
Gene: Protein-coding gene on chromosome 11 (114,400,030 to 114,414,203, forward strand). Ensembl gene ENSG00000076053.
Subcellular location: Nucleus, nucleoplasm; Nucleus
Subcellular location (Human Protein Atlas): Nucleoplasm
Pathways (Reactome):
Metabolism of RNA: Nuclear RNA decay; mRNA Splicing - Major Pathway
Gene expression (Transcription): Regulation of endogenous retroelements by the Human Silencing Hub (HUSH) complex
Gene Ontology:
Molecular function: 14-3-3 protein binding; pre-mRNA intronic binding; protein binding; RNA binding; snRNA binding; single-stranded RNA binding; nucleic acid binding
Biological process: snRNA catabolic process; regulation of alternative mRNA splicing, via spliceosome; RNA catabolic process
Cellular component: nuclear exosome targeting complex; nucleolus; nucleoplasm; nucleus
Genetic constraint (gnomAD): Loss-of-function variants: 11 observed, 23.8 expected, observed/expected ratio (o/e) 0.46, 90% interval 0.29 to 0.76. The upper end of that interval is the gene's LOEUF score, 0.76, which puts it in group 3 of 6, group 1 being the genes least tolerant of losing a copy. Missense variants: 222 observed, 293.18 expected, observed/expected ratio (o/e) 0.76, 90% interval 0.68 to 0.85. Synonymous variants: 95 observed, 101.77 expected, observed/expected ratio (o/e) 0.93, 90% interval 0.79 to 1.11.
Homologues: Orthologues: chimpanzee RBM7 (99% identical), macaque RBM7 (97% identical), pig RBM7 (91% identical), rabbit RBM7 (91% identical), dog RBM7 (89% identical), mouse Rbm7 (83% identical), rat Rbm7 (83% identical), guinea pig RBM7 (77% identical), zebrafish rbm7 (45% identical), Caenorhabditis elegans rnp-8 (24% identical), Caenorhabditis elegans rbm-7 (23% identical), Drosophila melanogaster CG11454 (22% identical). Paralogues in human: RBM11 (32% identical).